AR (androgen receptor)
Diseases named in the same sentence as AR in open-access papers (continued):
Sharing a sentence is not in itself a finding about the gene and the disease.
prostate carcinoma (continued). "Given its potent growth-inhibitory activity, we hypothesized that further dissecting the MeT-regulated transcriptome of MeT could yield new mechanistic insights into AR's tumor suppressive activity in prostate cancer." (PMID 36923279, 2022). "Androgen-activated AR regulates normal prostate physiology and prostate cancer pathophysiology." (PMID 35205640, 2022). "These similarities suggest that TR3 may control AR splicing events as PSF does in prostate cancer cells." (PMID 35454821, 2022). "Summary of AR status in 8194 pathology-confirmed prostate cancer cases." (PMID 36033483, 2022). "Compound 2-75 is a promising enzalutamide hybrid with HDAC inhibitory activity, which induced p21, led to higher acetyl-tubulin levels (based on stronger HDAC6 inhibition) than vorinostat, and suppressed Hsp90 and AR protein levels in C4-2 prostate cancer cells." (PMID 35582529, 2022). "As a result of the emerging concept of bacterial mimicry, we tested whether compounds with indole scaffolds capable of AhR activation have the potential to restrict AR activity in prostate cancer cells." (PMID 36613955, 2022). "Interestingly, a recent study investigated the role of AR reprogramming in regulating the lineage plasticity of prostate cancer." (PMID 36033483, 2022). "Interestingly, despite the ineffectiveness of ADT in CRPC, the majority of prostate cancers are still driven by AR as a result of several AR reactivation mechanisms." (PMID 35409187, 2022). "Besides KLK3e, we verified that there are many other AR‐regulated enhancer RNAs (AReRNAs) that are increased in castration‐resistant prostate cancer (CPRC) cells." (PMID 35170113, 2022). "Prostate cancer patients respond to androgen receptor (AR) inhibitors to a certain extent." (PMID 35549970, 2022). "The alteration of androgen receptor‐regulated signaling may affect prostate cancer development and progression." (PMID 35347810, 2022). "Overexpression of N-Myc in prostate cancer cells reduces the expression of AR and its target genes." (PMID 35886904, 2022). "The AR plays an important role in prostate cancer, even in the development of CRPC." (PMID 35413990, 2022). "NEPC is an aggressive variant of prostate cancer, characterized by the negative expression of AR and lower level of PSA." (PMID 35633416, 2022). "Moreover, fortunately, the availability of the approved AR inhibitors (e.g., enzalutamide, bicalutamide, abiraterone acetate, and seviteronel) used to treat prostate cancer creates a chance for AR-based drug repurposing for breast cancer." (PMID 36548336, 2022). "Therefore, in addition to its role as an epigenetic modifier that modulates prostate cancer cistromes, EZH2 also acts through additional direct and indirect mechanisms to regulate AR-driven prostate cancer progression." (PMID 36212399, 2022). "Since both GR and PPARγ have been linked to enhanced tumor growth, the increased expression of these nuclear receptors may help prostate cancer cells to overcome metformin-induced reductions in AR." (PMID 36175875, 2022). "Interestingly, CD44+/α2β1hi/CD133+ prostate cancer cells have self-renewal ability and can differentiate into prostate cells that can express AR and PAP." (PMID 35342431, 2022). "Thus, as is the case during HSPC, GATA2 contributes to prostate cancer growth during CRPC by amplifying the AR transcriptional program." (PMID 36212399, 2022). "In addition to AR, 2–75 downregulated the mutant AR-V7 in prostate cancer cells in a proteasome-dependent manner, implying that 2–75-treated cells had better AR breakdown." (PMID 36034650, 2022). "Similarly, SETD7 interacts directly with AR and enhances AR transcriptional activity by methylating its K632 residue, which is not only plays a proliferative role in prostate cancer but is also involved in TNFR and PTEN/PI3K/AKT signaling." (PMID 35812730, 2022).
prostate carcinoma (continued). "For instance, activated AR leads to a 50–450% increased glucose uptake in prostate cancer cells as it can induce the level of several genes encoding glucose transporters such as SLC2A1, SLC2A3, SLC2A10, and SLC2A12, and glycolytic genes such as HK1, HK2, PFK, PFKP, PFKFB2, and ENO1." (PMID 36551308, 2022). "In studies of human prostate cancer cell lines, activation of the androgen receptor (AR) increases expression of UAP1 such that similar regulatory machinery may be driving its high expression in plethodontid sperm." (PMID 35281090, 2022). "HOTAIR binds to the androgen receptor (AR) protein to block its interaction with the E3 ubiquitin ligase murine double minute 2, thereby preventing AR ubiquitination and protein degradation and contributing to castration-resistant prostate cancer." (PMID 35813070, 2022). "Genetic alterations of AR have been reported in up to 57.78% of advanced prostate cancer cases." (PMID 36050295, 2022). "We conclude that high translation rates are essential to maintain tumor heterogeneity in AR-low prostate cancer and may play a role in pro-tumorigenic cell-cell communication pathways." (PMID 36511483, 2022). "In addition to AR, the mutant AR-V7 was also downregulated by 2-75 in prostate cancer cells in a proteasome-dependent way, indicating enhanced AR degradation in 2-75-treated cells." (PMID 35582529, 2022). "An RNA-binding protein called LIN28 is involved in prostate cancer AR signaling." (PMID 36551557, 2022). "Overall, this study adds weight to the claim that raloxifene could be a potential treatment for AR-prostate cancer." (PMID 35453603, 2022). "At present, several PROTAC drugs have undergone or are undergoing clinical trials, including ARV-110 which targets the androgen receptor in prostate cancer, ARV-471, targeting the estrogen receptor in breast cancer, and FHD-609 which targets BRD9 in Synovial sarcoma." (PMID 36557960, 2022). "The greatest problem in the treatment of prostate cancer is the resistance of these cells to treatment aimed at inducing apoptosis, controlling signaling pathways responsible for cell proliferation or modulating the activity of the androgen receptor." (PMID 35055079, 2022). "LDs serve as temporary storage sites for cholesterol and so may influence AR-positive prostate cancer cell biology via other mechanisms." (PMID 35033184, 2022). "As a cytoplasmic kinase, ACK1 activates AR in prostate cancer." (PMID 35768871, 2022). "In prostate cancer, loss of TLE3 is associated with resistance to AR inhibitors." (PMID 36438567, 2022). "Additionally, ChIA-PET of RNA Pol II in prostate cancer cells revealed that the amplified AR locus further increases the number of chromatin interaction modules containing AR gene and its distal enhancer, which maximizes the upregulation of AR gene expression." (PMID 35966880, 2022). "In prostate cancer, androgen receptor (AR) has a central role in promoting the progression of prostate cancer and the inhibition of AR signaling by using androgen deprivation therapy (ADT) that represents the first treatment for castration-sensitive prostate cancer." (PMID 35565349, 2022). "Importantly, prostate cancer exists on a spectrum between AR-dependent and AR-independent disease, and both can simultaneously exist within the same patient." (PMID 36439451, 2022). "Thus, we tested sequential treatment of prostate cancer models with SPA followed by the AR inhibitor enzalutamide." (PMID 36194476, 2022). "In addition, BAP18 facilitates the recruitment of MLL1 subcomplex to the promoters of AR target genes to coactivate AR-mediated transcription in prostate cancer cells, thus promoting prostate cancer growth." (PMID 35484101, 2022). "Given that 5hmC has been suggested as a highly specific marker of lineage commitment during tissue development, and that prostate cancer can undergo lineage plasticity to escape AR-directed therapy, we next sought to evaluate 5hmC tissue specific markers in prostate cancer." (PMID 36251389, 2022).
prostate carcinoma (continued). "Additionally, it seems that different types of prostate cancer cells have shown different sensitivity to affecting the AR pathways through AhR activation." (PMID 36613955, 2022). "Therefore, identification of survival mechanisms facilitating adaptation of prostate cancer to an AR-indifferent state is an emerging need to prolong responses to ARPI." (PMID 35963852, 2022). "Moreover, targeting AR signaling was suggested to have the potential for treating many types of cancer, especially prostate cancer." (PMID 36235203, 2022). "Recently, transcriptomic data from nearly 20,000 tumors revealed that patients bearing a localized treatment-naïve primary prostate cancer with low AR-activity (AR-A; based on a signature of nine canonical AR transcriptional targets) experience a shorter time to recurrence." (PMID 35562350, 2022). "TMPRSS2-ERG and other rearrangements in prostate cancer cells may result from a molecular accident accompanying AR recruitment of the topoisomerase TOP2B to regulatory sequences near target genes during transcriptional activation." (PMID 35104804, 2022). "In addition, a study reported that LINE-1 ORF1p physically interacts with AR and modulate AR cytoplasm/nucleus translocation as well as promotes the proliferation of human prostate carcinoma cells in both ligand-dependent and independent manners." (PMID 35685648, 2022). "This extremely malignant progression may result from the lineage plasticity induced by adeno-PCa (prostate cancer) after androgen receptor (AR)-targeted therapy." (PMID 35464050, 2022). "In AR expressing prostate cancer cell lines, CWP232291 treatment significantly decreased the expression of the AR or AR splice variants (in LNCaP and VCaP cells, respectively), and anti-tumor activity was observed in four primary CRPC patient samples, including a docetaxel-resistant sample." (PMID 35204808, 2022). "In addition, mutations of the speckle type BTB/POZ protein SPOP, observed in about 10% of localized primary prostate cancers, have also been shown to drive the development of an oncogenic AR cistrome." (PMID 36212399, 2022). "Our study confirms a direct and equivalent cell-cycle inhibitory and cytotoxic effect of enzalutamide on AR-expressing vascular endothelial cells as reported on prostate cancer cells, which is reinforced by its observed capacity to inhibit vascular tubule formation in vitro." (PMID 35302608, 2022). "However, for breast and prostate cancer AR-signalling appears to have different functions according to the specific subtype, and disease stage." (PMID 35563746, 2022). "Collectively, our results suggest that inhibition of FKBP51 and FKBP52 activity might have a therapeutic effect on prostate cancer by abrogating AR dimer formation." (PMID 34057812, 2022). "Thus, the specific cofactors of AR and their subsequent roles in prostate carcinoma must be determined." (PMID 35444697, 2022). "Importantly, our analyses exposed a subtype of primary prostate cancer characterized by divergent AR (low) and MYC (high) transcriptional signatures that are predisposed to fail standard-of-care therapies and progress to the mCRPC stage." (PMID 35562350, 2022). "Therefore, CaMKK2 results overexpressed in prostate cancer as well, in part due to androgen-receptor hyperactivity." (PMID 35409187, 2022). "GZ17-6.02 interacted in a greater than additive fashion with olaparib to kill prostate cancer cells, regardless of androgen receptor expression or loss of PTEN function." (PMID 36408163, 2022). "Besides the promotive role of AR on the Warburg effect in prostate cancer cells, AR is also involved in many other processes that contribute to cancer cell metabolic reprogramming." (PMID 36551308, 2022).
prostate carcinoma (continued). "As a result, PSA is frequently elevated in patients with prostate cancer and has become a classic biomarker for disease diagnosis, whereas an AR-mediated transcription program increases cell proliferation and changes central metabolism and biosynthesis, leading to disease progression." (PMID 36209184, 2022). "Several studies found and interplay among AR and ncRNAs in prostate cancer and AR expression itself may be controlled by certain ncRNAs." (PMID 36111296, 2022). "However, to better dissect the role of HOXB13 in prostate cancer, both the clinical stage of the disease and the history of AR-targeting therapies should be considered when evaluating clinical data." (PMID 36212399, 2022). "Enzalutamide, an inhibitor of androgen receptor (AR) function, is a popular drug commonly prescribed to treat advanced prostate cancer, but resistant prostate cancer eventually develops which grow aggressively, leading to widespread metastatic disease and ends up with a lethal outcome." (PMID 34973338, 2022). "Thus, our study provides a better understanding of AR signaling in cellular plasticity in prostate cancer with neuroendocrine differentiation and allows new insights into therapeutic development." (PMID 36033483, 2022). "Moreover, it has been proven that IL-23 secreted by MDSCs drives castration-resistant prostate cancer by activating the androgen receptor pathway." (PMID 35211124, 2022). "To determine whether the changes in NAT10 in the drug treatment of prostate cancer cells are related to AR, we used AR-negative PC-3 cells and AR-positive VCaP cells for comparison." (PMID 35743017, 2022). "Neuroendocrine findings in prostate cancer patients are sometimes present at diagnosis, but may also arise after androgen deprivation or androgen receptor targeting." (PMID 36317631, 2022). "In prostate cancer cells, the effect of AR on the biology of this tumor is very well understood." (PMID 36361793, 2022). "Liquid biopsy of exosomes isolated from patients with prostate cancer revealed that exosomes are enriched for genes that are hallmarks of prostate cancer, such as androgen receptor, kallikreins (KLK2), cyclin-dependent kinase inhibitor 1A (CDKN1A), KLK10, JUN, and B2M (β2 microglobulin)." (PMID 36726968, 2022). "In these relapsed tumors, increased AR levels are frequently detected, and thus preventive approaches against AR expression or activity can reduce the morbidity and mortality of the frustrated prostate cancer." (PMID 35269825, 2022). "Treatment with androgen receptor antagonists or interfering with the synthesis of androgens remains the standard therapy for patients with advanced or metastatic forms of prostate cancer, as the prostate epithelium regresses after removal of androgens or blockade of the androgen receptor (AR)." (PMID 36551650, 2022). "ER and AR, ligand-dependent transcription factors, are activated by sex hormones and responsible for the regulation of cell proliferation, survival and differentiation in breast and prostate cancer, respectively." (PMID 35812730, 2022). "Indeed, in recent years, treatments of prostate cancer vastly improved towards androgen receptor targeted approaches." (PMID 36438817, 2022). "AR antagonists are currently the mainstay of treatments for prostate cancer." (PMID 36144603, 2022). "Both AR and TMPRSS2 are implicated in prostate cancer, and some data suggests that there may be an association between prostate cancer and depression and anxiety." (PMID 35444632, 2022). "Interestingly, targeting AR signaling has been widely investigated and potentially applied to treat multiple types of cancers, especially prostate cancer." (PMID 36013056, 2022).
prostate carcinoma (continued). "We have used AR-driven transcriptional networks to identify prostate cancer-relevant pathways." (PMID 35164752, 2022). "Similar to prostate cancer, our study found that both AR and SENP1 were highly expressed in Xp11.2 tRCC, and the transcript activity of the TFE3 fusion could be regulated by SENP1." (PMID 35452181, 2022). "FOXP1 is a prostate cancer suppressor that regulates androgen receptor and FOXA165." (PMID 36138066, 2022). "However, all this evidence indicated that ABCG2 maintains the characteristics of AR+ prostate cancer stem cells." (PMID 35342431, 2022). "Androgen deprivation therapies (ADTs) are important treatments which inhibit androgen-induced prostate cancer (PCa) progression by either preventing androgen biosynthesis (e.g. abiraterone) or by antagonizing androgen receptor (AR) function (e.g. bicalutamide, enzalutamide, darolutamide)." (PMID 36263323, 2022). "In addition, the nonsteroidal antiandrogen drug Casodex, which is used to treat advanced prostate cancer, represses the interaction between AR and CDC6, inhibiting DNA replication." (PMID 35743017, 2022). "AR-targeted therapies are effectively applied in prostate cancer." (PMID 35800434, 2022). "Moreover, expression of the AR gene in castration-resistant prostate cancer is induced compared to castration-sensitive types." (PMID 36235203, 2022). "The profile of AR target genes is different between benign and cancerous epithelial cells, between castrate-resistant prostate cancer cells and treatment-naïve cancer cells, between metastatic and primary cancer cells, and between epithelial cells and fibroblasts." (PMID 37435460, 2022). "In addition, some researchers recently found that AR can positively regulate the expression of miR-21 in prostate cancer, and there is a positive feedback loop between the regulation of AR and miR-21." (PMID 35573679, 2022). "However, in our study, we used the AR/NE signature score to redefine established prostate cancer cell lines into AR/DN/NEPC subtypes." (PMID 36672609, 2022). "The androgen receptor (AR), a ligand-inducible transcription factor, is key in controlling not only normal prostate homeostasis, such as cell proliferation and differentiation, but also prostate cancer initiation, growth, and progression." (PMID 35740556, 2022). "In prostate cancer, glucocorticoid receptor (GR) can activate part of AR signaling pathway, and inhibition of GR may be a potential target for the treatment of female reproductive system cancer." (PMID 35886904, 2022). "At diagnosis, prostate cancer is driven by the androgen receptor (AR)." (PMID 36561929, 2022). "Altogether, these findings show that ONECUT2 leads to AR independence in prostate cancer." (PMID 35582526, 2022). "In addition, there was a negative correlation between IGF1R and BRCA1 expression levels in AR-negative prostate cancer cells whereas in cells with an active AR there was a positive correlation." (PMID 35432218, 2022). "Finally, to further characterize the potential function of AR in neuroendocrine prostate cancer cells, we analyzed the single-cell transcriptome data of six CRPC patient samples previously reported by our center (GSE137829)." (PMID 36033483, 2022). "Thus, there is a need to discover treatments that target prostate cancer cells independently of the AR." (PMID 35453603, 2022). "The androgen receptor is the most important driver in human prostate cancer." (PMID 35109825, 2022). "In addition, CREB5 was shown to be a modulator of androgen receptor signals in prostate cancer cells, which can promote enzalutamide resistance in vivo and in vitro." (PMID 35773668, 2022). "It has been reported that AR can positively regulate the expression of miR-21 in prostate cancer." (PMID 35573679, 2022). "Androgen receptor (AR) drives prostate cancer (PCa) development and progression." (PMID 36450752, 2022).